FGFR1 (fibroblast growth factor receptor 1)
Diseases named in the same sentence as FGFR1 in open-access papers (continued):
Sharing a sentence is not in itself a finding about the gene and the disease.
Kallmann syndrome (continued). "It was molecularly proven in 25 (8 CHD7 mutations, 6 FGFR1 mutations, 7 ANOS1 mutations, 2 PROKR2 mutations, 1 digenic SOX10/SEMA3F mutation, and 1 digenic ROBO3/IGFS10 mutation with anosmia and later absent puberty)." (PMID 40193582, 2025). "FGFR1 is considered to be a pleiotropic gene that can display different roles during development and variants found in it can cause CHH with or without anosmia." (PMID 32982993, 2020). "In humans, mutations in FGF8 and FGFR1 are known to cause congenital hypogonadotropic hypogonadism (CHH) without or with anosmia, i.e. CHH+anosmia, septo-optic dysplasia or combined pituitary hormone deficiency, Hartsfield syndrome, holoprosencephaly and split hand/foot malformation." (PMID 35833364, 2022). "FGFR1 is one of the CHH-linked genes that is involved in both normosmic CHH and Kallmann Syndrome." (PMID 31996231, 2020).
non-small cell lung carcinoma (67 papers, 2011 to 2025). A group of at least three distinct histological types of lung cancer, including non-small cell squamous cell carcinoma, adenocarcinoma, and large cell carcinoma. "In short, we demonstrate that pemigatinib and KRAS G12C inhibitors are promising agents for combination therapy in non-small cell lung cancer with a mesenchymal-like phenotype harboring high FGFR1 expression and KRAS G12C mutations to broaden patient response." (PMID 40788860, 2025). "Studies for AZD4547 and BGJ389 revealed that patients with FGFR1 amplification (non-small cell lung cancer) or bearing FGFR3 mutations (bladder cancer) displayed a partial response to the therapy." (PMID 33898310, 2021). "This is interesting as the expression of bFGF and FGFR1 in non-small-cell lung carcinoma (NSCLC) is associated with tumor growth, invasion, and metastasis, although it is not related to the early stage of carcinoma." (PMID 32850408, 2020). "A meta-analysis and clinical survey suggest that FGFR1 is emerging as a diagnostic and prognostic marker for non-small-cell lung cancer (NSCLC)." (PMID 30484492, 2018). "In studies of non-small cell lung cancer, FGFR1 amplification has been significantly associated with shorter overall survival and shorter disease-free survival on univariate analysis but was not statistically significant on multivariate analysis." (PMID 29351293, 2018). "Amplification of FGFR1 occurs for instance, in non small cell lung cancer (NSCLC) and breast cancer, while mutations of FGFR3 are found in bladder and cervix carcinoma." (PMID 29152117, 2017). "In non-small-cell lung cancer, co-occurrence of FGFR1 amplification with EGFR alterations (amplification or mutations) has been observed in individual cases and small cohorts." (PMID 41514604, 2025). "FGFR1 amplification is particularly common, occurring in approximately 20% of non-small cell lung cancers (NSCLC) and 7% of urothelial carcinomas, leading to protein overexpression and oncogenic signaling dependency." (PMID 41304987, 2025). "This covalent binding inhibits FGFR1 activity, thereby blocking the PI3K/AKT/mTOR and RAS/MAPK pathways and suppressing the survival and proliferation of FGFR1-amplified and mutated non-small-cell lung cancer cells." (PMID 39590377, 2024). "In non-small cell lung cancer, hypoxia promotes the expression of fibroblast growth factor receptor 1 (FGFR1), which, in turn, sustains EGFR signal through the MAPK pathway." (PMID 37460927, 2023). "Amplification is the most common FGFR1 alteration and is prevalent in patients with breast and non-small cell lung cancers." (PMID 37493315, 2023). "The hazard ratio for progression-free survival of ALK-TKIs increased in patients with ALK fusion-positive non-small cell lung cancer with FGFR1- and FGF2-high mRNA expression at baseline." (PMID 37880373, 2023). "FGFR1 is amplified in an estimated 10% of breast cancers and 12% of non-small cell lung cancer (NSCLC), leading to a poor patient prognosis." (PMID 36147913, 2022). "circRNA fibroblast growth factor receptor 1 (circFGFR1), derived from FGFR1, was shown to have a high expression level in non-small cell lung cancer and was related to a poor prognosis and clinicopathological aspects." (PMID 36612180, 2022). "As FGFR1 is overexpressed in approx. 20% of non-small cell lung cancer, the NCI-H1703 non-small cell lung cancer cell line was used for further studies." (PMID 33898310, 2021). "Overexpression of FGFR1 in resistant to gefitinib (EGFR inhibitor) NSCLC (non-small-cell lung cancer) cells led to increased activation of AKT and mTOR, whereas FGFR1 inhibition decreased phosphorylation of both kinases and re-sensitized cells to gefitinib." (PMID 34830951, 2021). "Approximately 20% of all non-small cell lung cancer cases are characterised by FGFR1 amplification, indicating FGFR as a promising target for anti-cancer therapies." (PMID 34943871, 2021).
non-small cell lung carcinoma (continued). "FGFR1 amplification has been identified in 10–20% of patients with non-small cell lung cancer whereas 4–10% of primary gastric cancers and approximately 75% of bladder cancers harbor FGFR2 amplification and FGFR3 mutations, respectively." (PMID 33898310, 2021). "In afatinib-resistant non-small cell lung cancer cells, overexpression of FGFR1 and FGF2 played a role in overcoming cell survival by compensating the loss of the estrogen growth factor receptor (EGFR)-driven signalling pathway." (PMID 34830836, 2021). "Among four patients with FGFR1-amplified non-small-cell lung carcinoma, only one demonstrated partial responses." (PMID 34639155, 2021). "In order to investigate the intracellular behavior of the drug, the FGFR1-amplified non-small cell lung cancer cell lines NCI-H1703 and NCI-H520 were used." (PMID 30544798, 2018). "Pharmacological or genetic inhibition of FGFR1 by AZD4547 or FGFR1 short hairpin RNA (shRNA) induced autophagy in FGFR1-amplified non-small cell lung cancer (NSCLC) cells, H1581 and H520 cells." (PMID 28558758, 2017). "Although FGFR1 has recently emerged as a promising target in non-small cell lung cancer, data from CRC are limited." (PMID 28915719, 2017). "Further, Af23 and Ad23 significantly suppressed FGFR1 phosphorylation and cell proliferation in non-small-cell lung cancer (NSLCLC) H460 cells and induced cell apoptosis." (PMID 25880284, 2015). "FGFR1 kinase inhibitors have exhibited significant therapeutic effects against non-small-cell lung cancer." (PMID 25880284, 2015). "Amplification of the fibroblast growth factor receptor 1 (FGFR1) gene has been described in tumors of non-small-cell lung cancer (NSCLC) patients." (PMID 24255716, 2013). "Amplifications in FGFR1 (8p11) are most commonly present in squamous cell carcinoma, more common than other non-small cell carcinomas and associated with late-stage, but not necessarily with poor prognosis." (PMID 34068954, 2021). "Interestingly, as both genes were overexpressed in poorly differentiated cell lines, FGF2/FGFR1 activation in non-small-cell lung cancer has been proposed as an important EGFR-TKI-resistance-acquisition mechanism." (PMID 32517019, 2020). "Higher expression of the FGFR1 gene predicts poor overall survival and shorter disease-free survival in esophageal squamous cell carcinoma and similar results were observed in non-small-cell lung cancer, particularly squamous cell carcinoma." (PMID 32171280, 2020). "Moreover, in FGFR1-amplified non-small cell lung cancer cells, FGFR1 signaling contributes to maintenance of the CSC phenotype." (PMID 33066597, 2020). "Moreover, another study performed FISH analysis in 447 resected non-small cell lung cancer (NSCLC) tissue samples and SOX2 amplification was associated with increased gene copy number of FGFR1 and PI3KCA genes." (PMID 25114775, 2014). "In addition, pre-clinical studies on xenograft models transplanted with transformed cells derived from FGFR1-amplified non-small cell lung cancer (NSCLC) patients demonstrated that AZD4547 stops tumor growth and promotes regression." (PMID 23900974, 2013). "Moreover, in other solid tumors, such as non-small-cell lung cancer with FGFR1 amplification, the same alteration has been shown to induce “stem cell-like” characteristics, suggesting that this pathway exerts a conserved role in maintaining stemness across different tissue contexts." (PMID 41514604, 2025). "The most frequent type of FGFR1 aberrations is gene amplification, which is reported in 8.7–20.0% of non-small cell lung carcinoma (NSCLC) cases and involved in several acquired resistances against NSCLC therapeutics." (PMID 35494629, 2022). "In non-small cell lung cancer (NSCLC), for example, FGFR1 amplification has been reported in approximately 20% of cases, and its overexpression of up to 13% is associated with a more aggressive tumor phenotype." (PMID 40547805, 2025).
non-small cell lung carcinoma (continued). "In addition to patients with cholangiocarcinoma, we saw polyclonal acquired resistance in patients with FGFR2-altered gastroesophageal/gastroesophageal junction cancer and cancer of unknown primary origin, FGFR3-altered non-small cell lung cancer and FGFR1-altered pancreatic cancer." (PMID 38710951, 2024). "In this example, an investigator found a cellular receptor tyrosine kinase called Fibroblast Growth Factor Receptor 1 (FGFR1) and its downstream pathway to be upregulated in a subset of non-small cell lung cancer (NSCLC) samples." (PMID 36358671, 2022). "Recently, anlotinib hydrochloride, a new orally administered tyrosine kinase inhibitor, was found to have extensive advantages in treating non-small cell lung cancer by targeting KIT, VEGFA and FGFR1." (PMID 32427575, 2020). "Among the different lung tumors, non-small-cell lung cancer (NSCLC) is the most represented histotype, characterized by various molecular markers, including the expression/overexpression of the fibroblast growth factor receptor-1 (FGFR1)." (PMID 33317057, 2020). "In non-small cell lung cancer (NSCLC), FGFR1 amplification is detected at a rate of 6% (n = 63)." (PMID 34068954, 2021). "Nintedanib (BIBF 1120) is a potent, oral, small-molecule tyrosine kinase inhibitor of VEGFR-1/-2/-3, FGFR-1/-2/-3 and PDGFR-α/-β signaling, and has been recently approved for second line treatment of non-small cell lung cancer (NSCLC) of adenocarcinoma histology in combination with docetaxel." (PMID 27716819, 2016). "In addition, gefitinib sensitivity was also restored in non-small cell lung cancer cells when FGF2 and FGFR1 were inhibited via siRNA and treatment with a small molecule inhibitor, PD173074, suggesting FGFR activation as a potential mechanism of acquired resistance to EGFR-TKs." (PMID 34830836, 2021). "Additionally, genomic recombination can create FGFR1 fusion proteins, which are considered important oncogenic drivers in tumours like gastrointestinal stromal tumour (GIST), glioblastoma, breast cancer, bladder urothelial carcinoma or non-small cell lung cancer (NSCLC)." (PMID 40806483, 2025).
prostate carcinoma (64 papers, 2002 to 2026). A carcinoma that arises from epithelial cells of the prostate gland. "The overactivated FGFR1 signaling in Ac-Klf5–deficient and Pten-null prostate cancers can be attributed at least partly to the increased expression of FGF9." (PMID 38781024, 2024). "The findings in this study revealed that enhanced expression of Cx3cr1 after Klf5KR knockin in Pten-deficient prostate cancer is an endogenous molecular mechanism by which FGFR1 signaling is activated by its paracrine ligand FGF9." (PMID 38781024, 2024). "FGFR1 (Fibroblast GrowthFactor Receptor 1) has been linked to the development and progressionof various cancer types, including prostate cancer." (PMID 38739686, 2024). "Upregulation of FGF9 and CX3CR1 is associated with FGFR1 activation in Pten-deficient human prostate cancer." (PMID 38781024, 2024). "In summary, this study defines Klf5 acetylation at K358 as a PTEN deficiency–induced PTM, which constrains prostate cancer growth by attenuating FGFR1 activation." (PMID 38781024, 2024). "Collectively, FGF9 and CX3CR1 depended on each other to activate FGFR1 in PTEN-deficient prostate cancer." (PMID 38781024, 2024). "FGFR1 has also been shown to be associated with downregulation of choline kinase α and dysregulated choline metabolism, which promotes the progression of prostate cancer." (PMID 37750089, 2023). "Aberrant Fibroblast Growth Factor Receptor (FGFR) signaling has been implicated in advanced prostate cancer (PCa), and FGFR1 is suggested to be a promising therapeutic target along with current androgen deprivation therapy." (PMID 33456711, 2021). "Loss of the intrinsic FGF7/FGF10-type 2 FGF receptor (FGFR2) pathway and gain of the ectopic type 1 FGF receptor (FGFR1) pathway are associated with the progression to malignancy in prostate cancer (PCa) and many other epithelial originating lesions." (PMID 30761180, 2019). "Ectopic expression of FGFR1 in mouse prostate cancer model was shown to associate with the acquisition of an aggressive neuroendocrine phenotype and metastasis." (PMID 26673008, 2016). "Expression of FGFR1 is associated with increased proliferation and aggressive behavior of prostate cancer." (PMID 17137506, 2006). "Incident prostate cancer was associated with reduced methylation of the FGFR1 pathway." (PMID 38967555, 2024). "We therefore further evaluated whether FGF9 and CX3CR1 are associated with FGFR1 activation in PTEN-deficient human prostate cancer." (PMID 38781024, 2024). "We further focused on p-AKT+ samples to determine whether FGF9 is an active ligand of FGFR1 and whether CX3CR1 is required for FGFR1 activation in PTEN-deficient prostate cancer." (PMID 38781024, 2024). "Notably, FGF9 and CX3CR1 depended on each other to activate FGFR1 in PTEN-deficient human prostate cancer." (PMID 38781024, 2024). "However, a recent study found that the expression of the growth factor receptor FGFR1 was associated with indolent prostate cancer." (PMID 27966447, 2017). "Advanced biomimetic 3D in vitro models help replicate tumor-stroma interactions, introducing critical factors that influence tumor growth and invasiveness, like TGF-β1 and SDF-1 for breast cancer and FGFR1 for prostate cancer." (PMID 40606222, 2025). "In human prostate cancer samples, high FGF9 and CX3CR1 expression was jointly associated with the FGFR1 activation marker p-FRS2." (PMID 41514658, 2025). "The co-cultured cells retained tumor characteristics and continued expressing FGFR1 and FGF9, genes linked to aggressive prostate cancer and bone metastasis." (PMID 40606222, 2025). "In patients with prostate cancer, high expression levels of CX3CR1 were required for FGF9 to activate FGFR1 signaling, and CX3CR1 was positively associated with FGFR1 activation under FGF9 secretion." (PMID 38781024, 2024).
prostate carcinoma (continued). "Knockdown of CX3CR1 or blockage of CX3CR1 by different chemical inhibitors (AZD8797 and JMS-17-2) effectively suppressed FGFR1 activation and the formation of prostate cancer organoids." (PMID 38781024, 2024). "Functionally, knockdown of CX3CR1 suppressed the activation of FGFR1 signaling in DU 145 cells with KLF5WT and KLF5KR and attenuated the hyperactivation of FGFR1 signaling in KLF5KR-expressing prostate cancer cells." (PMID 38781024, 2024). "Collectively, FGF9 was a ligand of FGFR1 that was mainly released by CAFs and activated FGFR1 signaling in prostate cancer." (PMID 38781024, 2024). "In prostate cancer, the expression of FGFR1 is observed in approximately 20% of moderately differentiated cases and 40% of poorly differentiated cases." (PMID 38781024, 2024). "CX3CR1 inhibition blocked FGFR1 activation triggered by FGF9 and sensitized PTEN-deficient prostate cancer to the AKT inhibitor capivasertib." (PMID 38781024, 2024). "Our findings highlight a microenvironmental pathway for FGFR1 activation and provide a rationale for the combined therapy of AKT and FGFR1 inhibitors in prostate cancer treatment." (PMID 38781024, 2024). "Increased FGF9 and upregulated CX3CR1 cooperate to activate FGFR1 signaling, which leads to the progression of PTEN-deficient prostate cancer." (PMID 38781024, 2024). "Interruption of Klf5 acetylation in Pten-deficient prostate cancer cells signaled iCAFs through TNF-α to promote FGF9 release, which in turn activated FGFR1 signaling in prostate cancer cells." (PMID 38781024, 2024). "We found that these CM were capable of inducing FGFR1 activation in prostate cancer cells, as indicated by the phosphorylation of ERK and FGF receptor substrate 2 (FRS2)." (PMID 38781024, 2024). "FGF9 activated FGFR1 signaling in a dose-dependent manner within 15 minutes in DU 145 prostate cancer cells, as indicated by the phosphorylation of ERK and FRS2." (PMID 38781024, 2024). "Deacetylation of KLF5 in prostate cancer cells stimulated inflammatory cancer-associated fibroblasts (iCAFs) through TNF-α to release FGF9, which in turn activated FGFR1 signaling in prostate cancer cells." (PMID 38781024, 2024). "FGF23 expression was increased in patients with prostate cancer, as well as FGF23/FGFR1/αKlotho in various prostate cancer cell lines." (PMID 36926025, 2023). "Pre-clinical studies have demonstrated that FGFR1 is involved in prostate cancer progression and has a role in the metabolic reprogramming of prostate cancer cells." (PMID 38450313, 2023). "GREM1 binding to FGFR1 activated MEK/ERK signaling in prostate cancer cells, contributing to tumor progression and resistance to androgen deprivation." (PMID 37615860, 2023). "In prostate cancer, yes‐associated protein (YAP)/T‐box transcription factor 5 activates FGFR1 to mediate resistance to MET inhibitors." (PMID 37750089, 2023). "Although the expression of specific FGFR1 isoforms is generally overlooked in most published cancer studies, human pancreatic and prostate cancers have been reported to overexpress FGFR1 IIIc." (PMID 38136383, 2023). "FGFR1 amplification also plays a role in ovarian cancer, bladder cancer, renal cell carcinoma, prostate cancer, esophageal carcinoma, gastric cancer, colorectal cancer, pancreatic cancer, head and neck squamous cell carcinoma, and osteosarcoma." (PMID 37750089, 2023). "Correlation analysis showed that expression of circFGFR1int2 and FGFR1 RNA in prostate cancer were significantly correlated." (PMID 37993879, 2023). "A demonstration of GREM1-mediated activation of FGFR1 in vivo (independent from its inhibitory effect on BMP signaling) in prostate cancer would strengthen the argument that GREM1 promotes prostate cancer progression by activating FGFR1." (PMID 37615860, 2023). "FGFR1 was also critically important for enhanced NFκB signaling in prostate cancer cells, and this effect of FGFR1 was dependent on the stabilization of the TAK1 kinase." (PMID 34360000, 2021).